TRIM24 (tripartite motif containing 24)
Diseases named in the same sentence as TRIM24 in open-access papers (continued):
Sharing a sentence is not in itself a finding about the gene and the disease.
prostate carcinoma (31 papers, 2014 to 2025). A carcinoma that arises from epithelial cells of the prostate gland. "TRIM24 becomes stabilized in prostate cancer with SPOP mutations, through mechanisms involving TRIM28, upregulated in aggressive prostate cancer and associated with elevated TRIM24 levels: TRIM28 interacts with TRIM24 to prevent its ubiquitination and degradation by SPOP." (PMID 31366128, 2019). "TRIM24 is stabilized in SPOP-mutated prostate cancers, but the regulation of TRIM24 in wild-type prostate cancers is unknown." (PMID 30479348, 2018). "TRIM24 serves as an independent prognostic biomarker for prostate cancer, validated across two large independent cohorts." (PMID 39160596, 2024). "TRIM24 plays a crucial role in promoting cell proliferation in SPOP-mutant prostate cancer cells, particularly under conditions of low androgen availability." (PMID 39160596, 2024). "Further research showed that TRIM24 functions as a coactivator of the AR, playing a pivotal role in disease progression by acting as an oncogenic transcriptional activator in prostate cancer cells." (PMID 39160596, 2024). "This interaction results in TRIM24 accumulation and AR signaling activation, thereby promoting the tumorigenesis of prostate cancer." (PMID 39160596, 2024). "TRIM24 not only fosters prostate cancer growth but also sensitizes cells to low androgen levels by binding to gene promoters and activating pathways involved in both cell proliferation and AR signaling." (PMID 39160596, 2024). "TRIM24 plays a pivotal role in driving the proliferation of castration-resistant prostate cancer cells, aligning with the concept that AR co-activators sustain AR-mediated signaling during low hormone availability." (PMID 39160596, 2024). "TRIM24 promotes prostate cancer proliferation at low androgen conditions and bolsters androgen receptor signaling." (PMID 35105347, 2022). "TRIM24 mRNA levels were upregulated in prostate cancer cells (LNCaP, PC-3, C4-2) compared with those in RWPE-1 (P< 0.05); these were inversely associated with miR-655 expression and positively associated with Linc00963 expression in prostate cancer." (PMID 33643926, 2021). "TRIM24 has been identified as a direct target of miR-137, miR-374, miR-511, and miR-655 in prostate cancer and gastric cancer." (PMID 33643926, 2021). "In the current study, we further found TRIM24 was positively correlated with Linc00963 in prostate cancer, and was upregulated by Linc00963 in CRPC." (PMID 33643926, 2021). "In prostate cancer, as a key upstream regulator of TRIM24, TRIM28 was proved to interact with TRIM24 to prevent its ubiquitination and degradation by SPOP and also enhance the signal transduction of Androgen receptor (AR)." (PMID 33817325, 2021). "The interaction between BRD7 and TRIM24 in prostate cancer cells negatively regulates TRIM24 activity, and diminishes cell proliferation and cell growth." (PMID 32992509, 2020). "The increased Trim24 expression contributes to the progression of prostate cancer and is inversely related to the survival rate of breast cancer patients." (PMID 33336072, 2020). "The silencing of miR-137 increases the resistance of prostate cancer cells to androgen bicalutamide by directly upregulating TRIM24 expression." (PMID 33173411, 2020). "TRIM24 levels increase during prostate cancer progression, and the AR/TRIM24 gene signature as well as TRIM24 levels predict disease recurrence." (PMID 31366128, 2019). "TRIM24 protein augments AR signaling and promotes prostate cancer proliferation under low androgen conditions." (PMID 31366128, 2019). "TRIM24 is an effector substrate of the E3 ubiquitin ligase adaptor SPOP and becomes stabilized in prostate cancer (PCa) with SPOP mutations." (PMID 30479348, 2018). "Further, the transcriptional activator tripartite motif-containing 24 (TRIM24) is stabilized by speckle-type POZ protein (SPOP) mutations, which are often detected in recurrent prostate cancer." (PMID 28486411, 2017).
prostate carcinoma (continued). "TRIM24 expression was reported to be increased in prostate cancer tissues." (PMID 39160596, 2024). "Mutant SPOP enhances TRIM24 stability, which in turn drives prostate cancer cell growth." (PMID 39160596, 2024). "Additionally, the identification of bromodomain-containing 7 (BRD7), a negative regulator of cell proliferation and growth, represses the AR transactivation activity induced by TRIM24 and contributing to the modulation of prostate cancer pathogenesis." (PMID 39160596, 2024). "Additionally, Linc00963 promotes TRIM24 expression in castration-resistant prostate cancer cells by suppressing miR-655." (PMID 39768197, 2024). "Moreover, androgen receptor and TRIM24 co-activated genes are significantly upregulated in castration-resistant state prostate cancer." (PMID 35105347, 2022). "Notably, TRIM24 was positively correlated with cancer development and chemo-resistance in prostate cancer and glioma by activating the PI3K/AKT pathway." (PMID 33643926, 2021). "Moreover, two other TRIM proteins (TRIM33 and TRIM24) have been reported as oncogene or oncogenic transcriptional activators in B-cell leukemias and prostate cancer, respectively." (PMID 34284744, 2021). "We further investigated whether there was a regulatory mechanism between miR-655 and TRIM24 in prostate cancer." (PMID 33643926, 2021). "AR and Trim24 co-activated genes are found to be high expressed in prostate cancer." (PMID 33336072, 2020). "However, TRIM24 protein is located not only in the nucleus but also in the cytoplasm of prostate cancer cells, as displayed by immunofluorescence, indicating that TRIM24 protein plays different roles in different cancers." (PMID 27689360, 2016). "For example, TRIM24 is an oncogenic transcriptional activator in prostate cancer." (PMID 27888625, 2016). "Importantly, we further observed that depletion of SPOP with different sgRNAs could significantly elevate endogenous PDK1 protein levels, as well as well-established SPOP substrate Trim24 in prostate cancer cell lines." (PMID 34353330, 2021). "TRIM28 prevented TRIM24 from SPOP-mediated degradation, promoting the progression of prostate cancer." (PMID 34722282, 2021). "Previous studies have shown that TRIM28 protects TRIM24 from SPOP-mediated ubiquitin degradation and promotes the progression of prostate cancer." (PMID 34330324, 2021). "Previous studies have shown that both long intergenic non-coding RNA 00963 (Linc00963) and tripartite motif containing 24 (TRIM24) are activators of the PI3K/AKT pathway, and both are involved in the carcinogenesis and progression of prostate cancer." (PMID 33643926, 2021). "We found that TRIM24, an established oncogene in CRPC, was positively correlated with Linc00963 in prostate cancer tissues." (PMID 33643926, 2021). "The interaction between TRIM28 and TRIM24 protects TRIM24 from SPOP-mediated ubiquitin degradation and promotes the progression of prostate cancer." (PMID 34330324, 2021). "In SPOP-mutant prostate cancer, several dysregulated SPOP substrates (e.g., NCOA3, TRIM24, BET proteins) have been shown to boost the AR pathway leading ultimately to high levels of AR target genes 3,13,19–26." (PMID 33531470, 2021). "Here, the authors show that TRIM28 interacts with TRIM24 to prevent SPOP-mediated ubiquitination of TRIM24 and enhances TRIM24 and AR signaling to induce prostate cancer tumorigenesis." (PMID 30479348, 2018). "Similarly, TRIM24 can increase both PIK3CA and EGFR levels in human prostate cancer cell lines (LNCaP, PC-3, and C4-2), thereby facilitating the activation of the PI3K/AKT signaling pathway." (PMID 39768197, 2024).
prostate carcinoma (continued). "While the role of SPOP protein differs depending on the tumor type, in prostate cancer, SPOP seems to function as a tumor suppressor and its targets for degradation, among others, include AR, ERG, steroid receptor coactivator 3 (SRC3), BRD4, MYC, and TRIM24." (PMID 33572160, 2021). "Recurrent SPOP mutants stabilize TRIM24, enhancing AR signaling and promoting tumor growth via binding with the proteins TIP60 and BRD7, which has led to the proposition of TRIM24 as an essential gene for prostate cancer cell proliferation in CRPC." (PMID 29888169, 2018). "Interestingly, TRIM24 could function as transcriptional regulator of both PIK3CA and EGFR genes in prostate cancer, and that PIK3CA and EGFR had synergetic roles in activation of the PI3K/AKT pathway in prostate cancer and other types of tumors." (PMID 33643926, 2021).
hepatocellular carcinoma (23 papers, 2012 to 2025). A malignant tumor that arises from hepatocytes. "Diseases such as differentiated thyroid carcinoma, hepatocellular carcinomas, and cerebellar agenesis were associated with TRIM24." (PMID 34575874, 2021). "TRIM24 has been reported to undergo aberrant activation across a diverse spectrum of cancers, e.g., hepatocellular carcinomas, and breast, prostate and lung cancers." (PMID 41430038, 2025). "For instance, TRIM52, TRIM37, and TRIM47 have been linked to ovarian cancer invasion, while other members, such as TRIM37 in hepatocellular carcinoma and TRIM24 in colorectal cancer, are known to facilitate metastasis in other cancer types." (PMID 39937005, 2025). "In human hepatocellular carcinoma (HCC) tissues, increased expression of TRIM24 protein is observed, which is associated with poor differentiation, elevated α-fetoprotein levels, higher rates of intrahepatic metastasis and recurrence, and shorter tumor-free survival times." (PMID 39160596, 2024). "TRIM24 is associated with both oncogenic and tumor suppressive effects; deletion of TRIM24 promotes hepatocellular carcinoma in mice, while overexpression negatively correlates with cancer progression, including breast and prostate cancers." (PMID 36690785, 2023). "Studies in hepatocellular carcinoma and in non-small cell lung cancer cell lines had shown that down-regulation of TRIM24 induced by small interfering RNA can reduce the ability of migration and invasion, and reduce the expression of EMT-related proteins." (PMID 35105347, 2022). "Surprisingly, knocking-out TRIM24 also leads to hepatocellular carcinoma, suggesting that the right dose of the ligase is important for homeostasis." (PMID 33670160, 2021). "These include Trim24, a female-biased transcriptional regulator and tumor suppressor for hepatocellular carcinoma that is induced by cGH within 10 h, and Nox4, a cGH-repressed male-biased gene involved in liver oxidative stress and stellate cell activation." (PMID 28694329, 2017). "The protein expression of TRIM24 in human primary hepatocellular carcinoma and its relationship with clinicopathological factors have not yet been reported and, therefore, need to be discovered." (PMID 24409330, 2014). "On the other hand, recent studies showed that loss of TRIM24 in mice induces tumor development and that TRIM24 interacted with TRIM28 and TRIM33 to form regulatory complexes that suppressed murine hepatocellular carcinoma." (PMID 24409330, 2014). "Here we provide the first evidence of the expression profile and clinicopathological significance of TRIM24 in patients with hepatocellular carcinoma (HCC)." (PMID 24409330, 2014). "In this study, we report the TRIM24 expression in human hepatocellular carcinoma tissues by immunohistochemistry and effects of TRIM24 in apoptosis, cell cycle, and EMT in hepatocellular carcinoma cell line." (PMID 24409330, 2014). "In conclusion, this study investigated the expression and clinopathological significance of TRIM24 in human hepatocellular carcinoma." (PMID 24409330, 2014). "Further work is warranted to elucidate the mechanism of TRIM24 acting in the pathogenesis of hepatocellular carcinoma." (PMID 24409330, 2014). "Notably, TRIM24 determines the sensitivity of human hepatocellular carcinoma to etoposide-induced DSB at both the cellular level and in a xenograft tumor model." (PMID 39160596, 2024). "TRIM24, for instance, is overexpressed in breast cancer, non-small cell lung cancer, head and neck squamous cell carcinoma, glioma, gastric cancer, bladder cancer and hepatocellular carcinoma." (PMID 33670160, 2021). "Trim24 is a suppressor of mouse hepatocellular carcinoma; consequently, its elevated expression in female compared to male B6 mouse liver may contribute to the lower incidence of liver cancer in females." (PMID 34752452, 2021).
hepatocellular carcinoma (continued). "Contrastingly, TRIM24 was reported to act as a tumour suppressor in murine hepatocellular carcinoma (HCC) by dysregulating retinoic acid receptor (RAR) signalling, and it was later shown that TRIM24, TRIM28 and TRIM33 can form regulatory complexes to suppress murine HCC." (PMID 32731534, 2020). "TRIM24 (also known as TIF1α), belongs to the tripartite motif protein family, was reported to be aberrantly activated in a wide variety of cancers, including breast, head and neck, hepatocellular carcinomas and lung cancer." (PMID 28114950, 2017). "Notably, TRIM-28 and -33 form a multiprotein complex together with TRIM-24 that has been shown to act as tumor suppressor, for example, in the context of hepatocellular carcinoma." (PMID 25755299, 2015). "In addition, the biological roles of TRIM24 in hepatocellular carcinoma are still unclear." (PMID 24409330, 2014). "Two TRIMs, TRIM24 and TRIM33, described in isolation in this review are known to form a complex that co-operatively acts in tumour suppression in hepatocellular cancer cells." (PMID 29110249, 2018). "Moreover, in another similar mouse model with liver-specific complete deletion of TRIM24 (TRIM24hep/hep), hepatic lipid-filled lesions, steatosis, hepatic injury, fibrosis and hepatocellular carcinoma without high-fat diet are observed." (PMID 27689360, 2016). "However, recent studies showed that loss of TRIM24 in mice led to hepatocellular carcinoma development and TRIM24 interacted with TRIM28 and TRIM33 to form regulatory complexes that suppressed murine hepatocellular carcinoma, suggesting its role as a tumor suppressor in heptocellular carcinoma." (PMID 22666376, 2012). "Moreover, the complex plays a role in tumor suppression, as simultaneous inactivation of TRIM24 and TRIM33 in mice leads to the development of hepatocellular carcinoma (HCC), highlighting their cooperative function in regulating cellular processes beyond viral infection." (PMID 40421416, 2025).
glioma (18 papers, 2015 to 2025). A benign or malignant brain and spinal cord tumor that arises from glial cells (astrocytes, oligodendrocytes, ependymal cells). "Another study demonstrated that high TRIM24 expression is positively linked to increased glioma malignancy." (PMID 39160596, 2024). "Gain- and loss-of functions of NCK1-AS1, miR-138-2-3p and TRIM24 were performed to identify their roles in the behaviors of glioma cells." (PMID 32293515, 2020). "To assess whether of the association of TRIM24 with H3K23ac is required for glioma tumorigenesis, we conducted complementation experiments in LN229 and U87 GBM cells with TRIM24 shRNAs." (PMID 29129908, 2017). "Taken together, our data demonstrate that TRIM24 recruits STAT3 to chromatin in EGFR-driven glioma cells, which is dependent on H3K23ac association, thus providing evidence that TRIM24 binds with EGFR-upregulated H3K23ac, and then recruits STAT3 and stabilizes its interaction with chromatin." (PMID 29129908, 2017). "We present a case of high-grade glioma in a 6-year-old patient with a rare TRIM24::NTRK2-fusion, having had five tumor relapses in 4 years." (PMID 41331048, 2025). "TRIM24 plays a crucial role in glioma progression by influencing cell proliferation, cell cycle advancement, clone formation, and in vivo tumor development." (PMID 39160596, 2024). "Recently, the detection of the novel TRIM24::MET fusion in a particularly aggressive high-grade glial tumor in a neonate has been reported for the first time." (PMID 38902810, 2024). "Depletion of TRIM24 in glioma stem cells significantly reduced both p-STAT3 levels and cell proliferation, mirroring a similar phenotype observed in nasopharyngeal carcinoma cells." (PMID 39160596, 2024). "In glioma cells, TRIM24 recruits STAT3 as a transcriptional co-activator, stabilizing STAT3-chromatin interactions, which activates STAT3 downstream signaling and amplifies EGFR-driven cell proliferation." (PMID 39160596, 2024). "Here, the epigenetic regulator TRIM24 is identified as a driver of glioma progression, where TRIM24 overexpression promotes HRasV12 anaplastic astrocytoma (AA) progression into epithelioid GBM (Ep‐GBM)‐like tumors." (PMID 38828688, 2024). "In summary, this study presents a novel role of the epigenetic factor TRIM24 in glioma progression and Ep‐GBM‐like transformation." (PMID 38828688, 2024). "In this study, we identified the epigenetic regulator TRIM24, which cooperates with HRasV12 to regulate glioma progression." (PMID 38828688, 2024). "As a transcriptional co-activator of STAT3, TRIM24 leads to the activation of STAT3 downstream signaling in response to EGFR in glioma cells, ultimately supporting the stem cell-like phenotype." (PMID 36674511, 2023). "Here, we demonstrated that TRIM24 had higher expression levels at both the RNA and protein levels in glioma samples, and its expression was correlated with tumor histological subtypes in gliomas." (PMID 37367937, 2023). "For instance, regarding TRIM24, which functions as an oncogenic factor in gliomas, four inhibitors (Compound 34, IACS-6558, IACS-9571, and dTRIM24) have been developed so far." (PMID 36139694, 2022). "TRIM24 overexpression is characteristic of gliomas and is required for EGFR activation and for STAT3 recruitment and stabilization, which is important for exerting its oncogenic potential." (PMID 36139694, 2022). "Overexpression of TRIM24 (also known as TIF-1α) has been reported in high-grade gliomas (hGGs), such as anaplastic astrocytoma and GBM, compared to less malignant glial tumors and normal brain tissue." (PMID 36139694, 2022). "In our data, TRIM24 high expression correlated with cancer stemness in both lower-grade gliomas (LGG) and glioblastomas (GBM), as well as several other cancer types (BRCA, LUSC, STAD, and COAD)." (PMID 33810347, 2021). "In light of this theory and several recently identified ceRNA networks in cancers, the study figured out a novel NCK1-AS1/miR-138-2-3p/TRIM24 ceNRA network in glioma." (PMID 32293515, 2020).